FAM149B1 (family with sequence similarity 149 member B1)
Description:
Involved in the localization of proteins to the cilium and cilium assembly. Indirectly regulates the signaling functions of the cilium, being required for normal SHH/smoothened signaling and proper development.
Synonyms: KIAA0974; JBTS36
Tractability: No criterion of Open Targets' tractability assessment is met for any kind of drug.
Gene: Protein-coding gene on chromosome 10 (73,168,119 to 73,244,504, forward strand). Ensembl gene ENSG00000138286.
Subcellular location: Cell projection, cilium
Subcellular location (Human Protein Atlas): Microtubules; Primary cilium; Cytosol
Gene Ontology:
Molecular function: protein binding
Biological process: cilium assembly; protein localization to cilium
Cellular component: cilium
Genetic constraint (gnomAD): Loss-of-function variants: 37 observed, 49.68 expected, observed/expected ratio (o/e) 0.74, 90% interval 0.57 to 0.98. The upper end of that interval is the gene's LOEUF score, 0.98, which puts it in group 4 of 6, group 1 being the genes least tolerant of losing a copy. Missense variants: 450 observed, 499.39 expected, observed/expected ratio (o/e) 0.9, 90% interval 0.83 to 0.97. Synonymous variants: 200 observed, 192.37 expected, observed/expected ratio (o/e) 1.04, 90% interval 0.93 to 1.17.
Homologues: Orthologues: chimpanzee FAM149B1 (99% identical), macaque FAM149B1 (94% identical), pig FAM149B1 (88% identical), dog FAM149B1 (86% identical), mouse Fam149b (80% identical), rabbit FAM149B1 (80% identical), rat Fam149b1 (79% identical), guinea pig Fam149b1 (43% identical), zebrafish fam149b1 (40% identical), tropical clawed frog fam149b1 (38% identical). Paralogues in human: FAM149A (24% identical).
Diseases named in the same sentence as FAM149B1 in open-access papers:
FAM149B1 is named in the same sentence as 10 diseases in open-access papers, as found by Europe PMC text mining. Sharing a sentence is not in itself a finding about the gene and the disease. The quoted sentences say what the papers report.
Joubert syndrome (3 papers, 2021 to 2026). Joubert syndrome (JS) is characterized by congenital malformation of the brainstem and agenesis or hypoplasia of the cerebellar vermis leading to an abnormal respiratory pattern, nystagmus, hypotonia, ataxia, and delay in achieving motor milestones. "Biallelic truncating FAM149B1 variants result in cilia dysfunction and have been reported in four infants with Joubert syndrome and orofaciodigital syndrome type VI, respectively." (PMID 34828254, 2021). "Our study thus expands the FAM149B1-related Joubert syndrome to a mainly neurological and skeletal ciliopathy phenotype with predominant oculomotor dysfunction but otherwise stable outcome in adults." (PMID 34828254, 2021).
cerebellar ataxia (1 paper, 2021). A neurological syndrome characterized by clumsy and uncoordinated movement of the limbs, trunk, and cranial muscles. "Cerebellar ataxia, olfactory bulb aplasia and corpus callosal dysgenesis are novel neurological features associated with FAM149B1-related JS and all but olfactory aplasia are common features in other subtypes of JS." (PMID 34828254, 2021).
ciliopathy (1 paper, 2021). A genetic disorder of the cellular cilia or the cilia anchoring structures, the basal bodies, or of ciliary function. "Here we report the detailed clinical findings of three adults who are homozygous for the originally reported FAM149B1 p.Gln118Hisfs*20 variant and thereby expand the neurological, ocular and skeletal phenotype of the FAM149B1-reated ciliopathy beyond childhood." (PMID 34828254, 2021). "Developmental delay, intellectual disability, oculomotor apraxia, ptosis, and mesoaxial polydactyly were constant features in the four previously reported FAM149B1-related ciliopathy patients, while MTS and orofacial features were variably present." (PMID 34828254, 2021). "Due to the small number of reported patients and their young age at the time of publication, the phenotypic spectrum and the adult phenotype of the FAM149B1-related ciliopathy remained unclear." (PMID 34828254, 2021). "The absence of thoracic hypoplasia and of short stature in these siblings supports mild skeletal involvement in FAM149B1-related ciliopathy, highlighting the importance of performing skeletal radiographs to diagnose skeletal involvement." (PMID 34828254, 2021). "So far, only biallelic truncating FAM149B1 variants have been reported, and identification of further biallelic variants will be needed to define the phenotypic spectrum in FAM149B1-related ciliopathy." (PMID 34828254, 2021). "This study is the second report on FAM149B1-related ciliopathy and the first report on adult patients and expands the clinical spectrum and should increase awareness of this rare ciliopathy." (PMID 34828254, 2021).
ptosis (1 paper, 2021). The drooping of the upper eyelid. "Unlike to the previously reported patients, ptosis and polydactyly were present in one patient each in the study presented here and OFD VI-related oral anomalies were not present, indicating phenotypic variability in FAM149B1-related JS." (PMID 34828254, 2021).
FAM149B1 also shares sentences with these, for which no sentence is quoted: Anosmia (1 paper); Ataxia (1); Nystagmus (1); polycystic kidney disease (1); retinopathy (1); skeletal dysplasia (1).